FAM151A (family with sequence similarity 151 member A)
Synonyms: C1orf179; MGC27169
Tractability: Antibody: UniProt predicts a signal peptide or a membrane-spanning region. PROTAC: its protein half-life has been measured.
Gene: Protein-coding gene on chromosome 1 (54,609,178 to 54,623,556, reverse strand). Ensembl gene ENSG00000162391.
Subcellular location: Membrane
Gene Ontology:
Cellular component: extracellular exosome; membrane
Genetic constraint (gnomAD): Loss-of-function variants: 42 observed, 45.15 expected, observed/expected ratio (o/e) 0.93, 90% interval 0.73 to 1.2. The upper end of that interval is the gene's LOEUF score, 1.2, which puts it in group 5 of 6, group 1 being the genes least tolerant of losing a copy. Missense variants: 740 observed, 775.37 expected, observed/expected ratio (o/e) 0.95, 90% interval 0.9 to 1.01. Synonymous variants: 337 observed, 327.18 expected, observed/expected ratio (o/e) 1.03, 90% interval 0.94 to 1.13.
Homologues: Orthologues: chimpanzee FAM151A (98% identical), macaque FAM151A (95% identical), pig FAM151A (74% identical), dog FAM151A (73% identical), mouse Fam151a (71% identical), rat Fam151a (71% identical), rabbit FAM151A (68% identical), tropical clawed frog fam151a (44% identical), zebrafish fam151a (42% identical), Drosophila melanogaster CG7231 (17% identical), Caenorhabditis elegans mnr-1 (17% identical). Paralogues in human: FAM151B (21% identical).
Diseases named in the same sentence as FAM151A in open-access papers:
FAM151A is named in the same sentence as 7 diseases in open-access papers, as found by Europe PMC text mining. Sharing a sentence is not in itself a finding about the gene and the disease. The quoted sentences say what the papers report.
lung squamous cell carcinoma (1 paper, 2025). "Pan-cancer analysis showed that CCDC68, FAM151A and MC1R were significantly different in thyroid cancer (THCA), renal clear cell carcinoma (RCC) and lung squamous cell carcinoma (LUSC) etc.." (PMID 40547309, 2025).
FAM151A also shares sentences with these, for which no sentence is quoted: cancer (2 papers); COVID-19 (1); cutaneous T-cell lymphoma (1); renal clear cell carcinoma (1); retinal degeneration (1); thyroid cancer (1).